CYB5R3 (cytochrome b5 reductase 3)
Diseases named in the same sentence as CYB5R3 in open-access papers (continued):
Sharing a sentence is not in itself a finding about the gene and the disease.
lung fibrosis (1 paper, 2023). "To confirm the susceptibility to lung injury and fibrosis of the Cyb5r3-deficient mice, we used a different model of lung injury, the bleomycin-induced lung fibrosis model." (PMID 36749633, 2023). "Deficiency of Cyb5r3 in the AECII increases susceptibility to lung fibrosis." (PMID 36749633, 2023). "We subjected Cyb5r3fl/fl and Cyb5r3 SPC–KO mice to our model of lung fibrosis by infection with the murine gammaherpesvirus 68 (MHV68)." (PMID 36749633, 2023). "Deficiency of CYB5R3 in AECIIs led to sustained activation of the pro-fibrotic factor TGF-β1 and increased susceptibility to lung fibrosis." (PMID 36749633, 2023). "Together, these data suggested that CYB5R3 has an important role maintaining AECIIs’ homeostasis and it can be linked to TGF-β signaling that might affect vulnerability to lung injury and development of lung fibrosis." (PMID 36749633, 2023). "The results from this study link CYB5R3 deficiency to the upregulation of pro-fibrotic TGF-β1 signaling, suggesting that strategies aiming at CYB5R3 expression and activity, such as the use of sGC agonists, may lessen the severity of pulmonary fibrosis, specifically in the context of the aging lung." (PMID 36749633, 2023). "Therapeutic interventions aimed at restoring mitochondrial health do not improve virus-induced lung fibrosis in SPC-specific Cyb5r3-KO mice." (PMID 36749633, 2023).
neuroblastoma (1 paper, 2018). Neuroblastoma (NB) is the most common solid, extracranial childhood tumor. "CYB5R3 is nowadays recognized as a pivotal enzyme in the survival of human neuroblastoma cells undergoing metabolic and oxidative stress." (PMID 30309019, 2018). "Furthermore, it has been proved that CYB5R3 plays a clear role in mitochondrial homeostasis in fibroblasts from type II RHM patients, CYB5R3-silenced human cells, and CYB5R3-overexpressed human neuroblastoma cells." (PMID 30309019, 2018).
Obesity (1 paper, 2024). Accumulation of substantial excess body fat. "Overall, our results confirmed the critical role of liver CYB5R3 in cholesterol dyshomeostasis via APOO knockout, but not in obesity." (PMID 38830896, 2024).
pulmonary hypertension (1 paper, 2023). Increased pressure within the pulmonary circulation due to lung or heart disorder. "Heme-related generation of ROS decreases availability and or activation of soluble guanylyl cyclase or its regulators such as cytochrome b5 reductase 3 (CYB5R3), which can result in poor vasodilation of pulmonary vasculature, increasing the risk of pulmonary hypertension." (PMID 36830749, 2023).
vasculitis (1 paper, 2023). "Analysis of lung pathology of Cyb5r3fl/fl infected mice showed limited interstitial pneumonia and vasculitis while Cyb5r3 SPC–KO mice developed extended areas of interstitial fibrosis, which correlated with higher collagen deposition measured by levels of hydroxyproline." (PMID 36749633, 2023).
ventricular fibrillation (1 paper, 2022). A disorder characterized by an electrocardiographic finding of a rapid grossly irregular ventricular rhythm with marked variability in QRS cycle length, morphology, and amplitude. "The increase in SCD in CYB5R3-KO mice is associated with calcium mishandling, ventricular fibrillation, and cardiomyocyte hypertrophy." (PMID 36106636, 2022).
tumor (14 papers, 1996 to 2025). "Their study suggested that CYB5R3 may be directly involved in the development of other tumours associated with aromatic and heterocyclic amine exposures, such as CRC." (PMID 36008952, 2022). "CYB5R3 has been associated with mitochondrial dysfunction in cancer, a process that has been shown to play a context-dependent role in the promotion of tumor growth." (PMID 24495353, 2014). "The properties of CYB5R3 as a tumor suppressor in cancer cells can be exploited to develop anticancer drugs." (PMID 38253797, 2024). "It is worth noting, however, that this study also reported a contradictory finding with CYB5R3 overexpression contributing to increased tumor size." (PMID 36441026, 2022). "Inhibition of either of CYB5R3 or MYLK could be effective at halting tumor progression because the inhibition of one of these genes should modulate the expression of the other." (PMID 24944582, 2014). "Therefore, further studies are required to explore the role of CYB5R3 in tumor metabolism." (PMID 38253797, 2024). "In addition, the knockdown of Myh9, Cyb5r3, or RPS3A inhibited tumorigenicity and tumor growth in a subcutaneous xenograft tumor model under HFD conditions." (PMID 40470795, 2025). "Moreover, five genes, including the SLC12A4, SLIT3, GYPC, TSPAN4, CYYBRD1, CYB5R3, and FBLN5 were identified as co-expressed in the healthy and tumor tissue groups." (PMID 37365287, 2023). "The genes with the highest influence are the transmembrane protein TMEM14A in the untreated tumor samples, the zinc-finger transcription factor ZFHX4 following 14 days of letrozole treatment, and the redox protein CYB5R3 following 90 days of letrozole treatment." (PMID 24495353, 2014).
cancer (13 papers, 1996 to 2025). A tumor composed of atypical neoplastic, often pleomorphic cells that invade other tissues. "CYB5R3 has also been implicated in various cancers over the past decade." (PMID 36441026, 2022). "Genes involved in mitogen‐activated protein kinase (MAPK) signaling, the TNF signaling pathway, pathways in cancer, protein processing in ER, and the apoptosis pathway were upregulated in CYB5R3-overexpressing cells." (PMID 38253797, 2024). "On the other hand, CYB5R3 played a key role in the extravasation and colonization of cancer cells in mice." (PMID 38791014, 2024). "TCGA data analysis revealed that CYB5R3 mRNA expression was significantly decreased in 13 of 24 subtypes of cancer tissues compared to the corresponding normal tissues in patients represented in TCGA." (PMID 38253797, 2024). "To investigate the molecular mechanism by which CYB5R3 induces cancer cell death, we analyzed the gene expression pattern induced by CYB5R3 overexpression in H1299 cells." (PMID 38253797, 2024). "Although the role of CYB5R3 in cancer remains controversial, a previous study showed that CYB5R3 promotes cell colonization and metastasis formation in estrogen receptor-negative breast cancer." (PMID 38253797, 2024). "Several studies have highlighted CYB5R3 overexpression in cancer cells to protect against oxidative stress and apoptosis." (PMID 36441026, 2022). "On the other hand, AFR should be rapidly eliminated in the mitochondrial environment of cancer cells due to overexpressed Cyb5R3/VDAC1 [,9] and high cytosolic levels of NADH as an electron donor." (PMID 31678721, 2020). "It is interesting to note that Cyb5R3-siRNA-silenced cancer cells stop proliferation and metastasis, but they continue to survive." (PMID 32411317, 2020). "On the other hand, AFR should be rapidly eliminated in the mitochondrial environment of cancer cells due to overexpressed Cyb5R3/VDAC1 and high cytosolic levels of NADH as an electron donor." (PMID 32411317, 2020). "Overexpression of the Cyb5R3/VDAC1 appears to be a compensatory mechanism that protects cancer cells and their mitochondria by regulating AFR accumulation at “steady-state” conditions, while also maintaining the cytosolic NAD+/NADH ratio." (PMID 31678721, 2020). "It was found that the OMM Cyb5R3 is overexpressed in cancer cells, protecting them against oxidative stress and induction of apoptosis." (PMID 31678721, 2020). "Is AFR harmful for mitochondria and can pharmacological doses of vitamin C attack cancer cells by inhibiting membrane-bound Cyb5R3 and impairing mitochondrial respiration?" (PMID 32411317, 2020). "Some cancers may be sheltered from oxidative stress and apoptosis if CYB5R3 is overexpressed in these tumors." (PMID 38074856, 2023). "Previous studies have linked CYB5R3 and CLIP4 to cancer diagnosis and prognosis." (PMID 38074856, 2023). "No influence of two genes (CYB5R3 and HEXB) in cancers has been reported, but our study found that upregulation of CYB5R3 and HEXB was significantly linked to the poor prognosis of HCC patients." (PMID 34557495, 2021). "Cyb5R3 belongs to the class of cancer-related and disease-related genes." (PMID 31678721, 2020). "Single reports on the role of OMM Cyb5R3 in cancer have appeared over the past 10 years." (PMID 32411317, 2020). "A large cohort study on patients with estrogen receptor-negative (ERneg) and progesterone receptor-negative (PRneg) breast tumors reveals a central role of membrane-bound Cyb5R3 in extravasation/colonization of cancer cells and metastasis formation at distinct sites (e.g., lung)." (PMID 32411317, 2020). "A decline in expression of a number of messenger RNAs involved in cell cycle progression was observed in CYB5R3 livers, which led us to ascertain whether CYB5R3 overexpression confers protection against cancer development." (PMID 28721264, 2016). "However, the role of CYB5R3 in cancer development remains poorly understood." (PMID 38253797, 2024).
cancer (continued). "Moreover, CYB5R3 overexpression is described in cancer cells of the lung." (PMID 36441026, 2022). "The function of membrane-bound cytochrome b5 reductase 3 (CYB5R3) and hexosaminidase subunit beta (HEXB) on cancers is still unclear." (PMID 34557495, 2021). "Can high doses of vitamin C attack cancer cells only by inhibiting Cyb5R3/VDAC1 and specific destruction of cancer mitochondria?" (PMID 31678721, 2020). "We suppose that high “therapeutic” intracellular concentration of ascorbate in cancer cells is then likely to induce “enzyme (Cyb5R3) end-product inhibition” – a negative feedback, regulating any enzymatic pathway." (PMID 31678721, 2020). "However, the functions and mechanisms of CYB5R3 in cancer biology have not yet been explored." (PMID 38253797, 2024).
infection (5 papers, 2021 to 2026). The state of being infected such as from the introduction of a foreign agent such as serum, vaccine, antigenic substance or organism. "CYB5R3 protein expression was detectable within 12 h and showed the highest values 24 h after infection with CYB5R3." (PMID 38253797, 2024). "Higher collagen deposition after infection in Cyb5r3 SPC–KO mice was accompanied by significantly higher transcript levels of Mmp12, Mmp13, Mmp14, and tissue inhibitor of metalloproteinases 1 (Timp1) but neither Timp2 nor Timp3." (PMID 36749633, 2023). "Similar results were obtained if the sGC agonist diets were introduced as a preventive treatment (3 days prior to infection), leading to a substantial decrease in the severity of lung damage and fibrosis in the Cyb5r3 SPC–KO mice after infection." (PMID 36749633, 2023). "In addition, no significant changes in Cyb5r3 expression were found after infection." (PMID 36749633, 2023).
cardiovascular disease (2 papers, 2022). "While the importance of human CYB5R3 function to development is evident, the significance of CYB5R3 in the cardiovascular system and its potential in human cardiovascular disease has not been fully elucidated." (PMID 36106636, 2022).
neurological disease (2 papers, 2018 to 2023). "Defective CYB5R3 leads to defects in the elongation and desaturation of fatty acids and cholesterol biosynthesis, which are conventionally linked with neurological disorders of type II RHM." (PMID 30309019, 2018). "Thus, the control of aerobic metabolism and the cytosolic NAD+/NADH ratio by CYB5R3 could provide a key regulatory function in the maintenance of neuronal health and, accordingly, a defect of this mechanism of action could be directly related to the neurological disorders in type II RHM." (PMID 30309019, 2018).
adenocarcinoma (1 paper, 2024). A common cancer characterized by the presence of malignant glandular cells. "In moderate and poor adenocarcinomas, the expression of the CYB5R3 gene, but not CYB5R1 and CYB5R2/4, was decreased." (PMID 38791014, 2024).
heart disease (1 paper, 2022). "While new functional pathways for CYB5R3 are under investigation, no reports have defined the significance of CYB5R3 in cardiomyocytes or the translational impact of modulating CYB5R3 activity in humans with heart disease." (PMID 36106636, 2022).
CYB5R3 also shares sentences with these, for which no sentence is quoted: metabolic disease (2 papers); age (1); Atrophy (1); autism (1); Cerebellar atrophy (1); diabetes (1); Duchenne muscular dystrophy (1); genetic disease (1); hepatocellular carcinoma (1); Hip dysplasia (1); inflammation (1); Lewis lung carcinoma (1); lung squamous cell carcinoma (1); papillary thyroid cancer (1); pontocerebellar hypoplasia (1); renal carcinoma (1); schizophrenia (1); Stroke (1).